ACCSL (1-aminocyclopropane-1-carboxylate synthase homolog (inactive) like)
Tractability: No criterion of Open Targets' tractability assessment is met for any kind of drug.
Gene: Protein-coding gene on chromosome 11 (44,047,981 to 44,059,977, forward strand). Ensembl gene ENSG00000205126.
Subcellular location (Human Protein Atlas): Cytosol
Gene Ontology:
Molecular function: pyridoxal phosphate binding
Genetic constraint (gnomAD): Loss-of-function variants: 52 observed, 63.21 expected, observed/expected ratio (o/e) 0.82, 90% interval 0.66 to 1.04. The upper end of that interval is the gene's LOEUF score, 1.04, which puts it in group 4 of 6, group 1 being the genes least tolerant of losing a copy. Missense variants: 620 observed, 721.6 expected, observed/expected ratio (o/e) 0.86, 90% interval 0.8 to 0.92. Synonymous variants: 256 observed, 273.39 expected, observed/expected ratio (o/e) 0.94, 90% interval 0.85 to 1.04.
Homologues: Orthologues: chimpanzee ACCSL (98% identical), macaque ACCSL (94% identical), pig ACCSL (64% identical), rabbit ACCSL (64% identical), mouse Accsl (56% identical), Caenorhabditis elegans T04F3.1 (22% identical), Drosophila melanogaster CG1640 (13% identical), Drosophila melanogaster CG6321 (13% identical), Caenorhabditis elegans nkat-3 (13% identical), Caenorhabditis elegans C32F10.8 (12% identical), Caenorhabditis elegans nkat-1 (10% identical). Paralogues in human: ACCS (43% identical), AADAT (15% identical), GPT (15% identical), GPT2 (14% identical), TAT (14% identical), KYAT3 (12% identical), KYAT1 (12% identical).
Diseases named in the same sentence as ACCSL in open-access papers:
ACCSL is named in the same sentence as 2 diseases in open-access papers, as found by Europe PMC text mining. Sharing a sentence is not in itself a finding about the gene and the disease.
ACCSL shares sentences with these, for which no sentence is quoted: developmental delay (1 paper); hypopituitarism (1).